VGLL2 (vestigial like family member 2)
Description:
May act as a specific coactivator for the mammalian TEFs. May play a role in the development of skeletal muscles.
Synonyms: VITO1; VGL2
Tractability: No criterion of Open Targets' tractability assessment is met for any kind of drug.
Gene: Protein-coding gene on chromosome 6 (117,265,558 to 117,273,618, forward strand). Ensembl gene ENSG00000170162.
Subcellular location: Nucleus
Gene Ontology:
Molecular function: protein binding; transcription coactivator activity
Biological process: regulation of transcription by RNA polymerase II; positive regulation of DNA-templated transcription; regulation of DNA-templated transcription
Cellular component: nucleus; cytoplasm
Genetic constraint (gnomAD): Loss-of-function variants: 18 observed, 21.89 expected, observed/expected ratio (o/e) 0.82, 90% interval 0.57 to 1.22. The synonymous counts are far from expectation, so gnomAD's model fits this gene poorly and the ratio says little. Missense variants: 491 observed, 354.78 expected, observed/expected ratio (o/e) 1.38, 90% interval 1.28 to 1.49. Synonymous variants: 220 observed, 159.16 expected, observed/expected ratio (o/e) 1.38, 90% interval 1.24 to 1.55.
Homologues: Orthologues: macaque VGLL2 (98% identical), chimpanzee VGLL2 (97% identical), pig VGLL2 (95% identical), rabbit VGLL2 (94% identical), dog VGLL2 (93% identical), mouse Vgll2 (86% identical), rat Vgll2 (85% identical), tropical clawed frog vgll2 (69% identical), zebrafish vgll2a (59% identical), guinea pig VGLL2 (55% identical), Drosophila melanogaster vg (26% identical). Paralogues in human: VGLL3 (38% identical), VGLL1 (21% identical).
Diseases named in the same sentence as VGLL2 in open-access papers:
VGLL2 is named in the same sentence as 11 diseases in open-access papers, as found by Europe PMC text mining. Sharing a sentence is not in itself a finding about the gene and the disease. The quoted sentences say what the papers report.
rhabdomyosarcoma (4 papers, 2021 to 2025). A rare aggressive malignant mesenchymal neoplasm arising from skeletal muscle. "In this case, the diagnosis of spindle cell/sclerosing rhabdomyosarcoma was confirmed based on the histopathological characteristics, immunohistochemical analysis, and positive VGLL2-CITED2 molecular detection." (PMID 41158453, 2025). "Alaggio and coworkers identified VGLL-2-related fusions in spindle cell/sclerosing rhabdomyosarcoma in children." (PMID 36173721, 2022). "Spindle cell/sclerosing rhabdomyosarcomas typically harbor certain genomic alterations, including rearrangements involving TFCP2, VGLL2, NCOA2, CITED2, TEAD1, and SRF, as well as the MYOD1 p.L122R mutation." (PMID 40361368, 2025). "Postoperative pathological examination, incorporating morphological and immunohistochemical analyses, as well as confirmation of positive VGLL2-CITED2 fusion, established the diagnosis of spindle cell/sclerosing rhabdomyosarcoma." (PMID 41158453, 2025).
spindle cell rhabdomyosarcoma (4 papers, 2021 to 2025). An uncommon variant of rhabdomyosarcoma characterized by the presence of whorls of spindle cells forming a storiform pattern. "Secondly, the infant/congenital subtype of spindle cell rhabdomyosarcoma harbours fusions of VGLL2::NCOA2 or VGLL2::CITED, which occur in up to two-thirds of cases, and rarer TEAD1::NCOA2 fusions have also been reported." (PMID 40983796, 2025). "Several recent studies have identified the recurrent rearrangement of the VGLL2 and TEAD1 genes in a large subset of spindle cell rhabdomyosarcoma (scRMS), a pediatric form of RMS that is distinct from embryonic RMS (ERMS)." (PMID 38746415, 2025).
sarcoma (2 papers, 2020 to 2025). A usually aggressive malignant neoplasm of the soft tissue or bone. "Sarcomas harboring VGLL2-fusion genes shared similar gene expression signatures, suggesting that the common region of these fusion genes, namely VGLL2, plays an important role in the development of sarcoma." (PMID 32793503, 2020). "The analyses of the molecular roles of VGLL2-fusion genes are required to evaluate their significance in sarcoma development." (PMID 32793503, 2020). "VGLL1 dysregulation was detected in various types of tumor; however, gene alterations in VGLL2 and VGLL3 were observed specifically in sarcoma." (PMID 32793503, 2020). "Similarly to VGLL2, VGLL3 gene alterations were identified in sarcoma." (PMID 32793503, 2020).
metabolic syndrome (1 paper, 2023). A cluster of metabolic risk factors for CARDIOVASCULAR DISEASES and TYPE 2 DIABETES MELLITUS. "In addition, GWAS analyses in human metabolic syndrome discovered the association of the strawberry notch homolog 1 (SBNO1) gene on plasma high-density lipoprotein cholesterol concentration, whereas the vestigial like family member 2 (VGLL2) gene was linked to the fatty acids profile in sheep." (PMID 37141193, 2023).
Sepsis (1 paper, 2022). Sepsis is defined as life-threatening organ dysfunction caused by a dysregulated host response to infection. "Interestingly, VGLL2 has also been shown to be associated with an age-dependent response to sepsis in the hearts of mice." (PMID 36587059, 2022).
tumor (6 papers, 2020 to 2025). "In a follow-up study characterizing spindle-cell infantile/pediatric RMS tumor specimens, additional fusions were identified including VGLL2::NCOA2, VGLL2::CITED2, TEAD1::NCOA2, and SRF::NCOA2." (PMID 40599857, 2025). "Patients aged <1 year with VGLL2, SBF, TEAD1, and NCOA2 gene fusions had a better prognosis, whereas patients with a MYOD1 gene mutation demonstrated stronger tumor aggression and higher mortality, regardless of age." (PMID 36686750, 2022).
VGLL2 also shares sentences with these, for which no sentence is quoted: autism (1 paper); cancer (1); Duchenne muscular dystrophy (1); glioma (1); rhabdoid tumor (1).